MYC (MYC proto-oncogene, bHLH transcription factor)
Diseases named in the same sentence as MYC in open-access papers (continued):
Sharing a sentence is not in itself a finding about the gene and the disease.
cancer (continued). "Dysregulated expression of MYC genes are frequently observed in cancers of different origin, implicating that MYC proteins have central functions during carcinogenesis." (PMID 33585251, 2020). "MYC and RB1 overwhelmingly feature either heavy gene amplifications or heavy deletions and mutations, respectively, across different cancer types." (PMID 33266490, 2020). "It was also reported that some drugs with antitumor activity, such as R-2-hydroxyglutarate (R-2HG), inhibited proliferation/survival of FTO-high cancer cells via targeting FTO/m6A/MYC/CEBPA signaling." (PMID 32754191, 2020). "Although MYC is a highly desirable target for anti-cancer drug development, there has been a lot of challenges that have held back the development of drugs directly targeting MYC." (PMID 33081056, 2020). "JQ1 shows good efficacy in multiple MYC cancers as well as MYCN overexpressed CNS tumors such as MBs and NBs." (PMID 33585252, 2020). "For example, the combination of a PARP inhibitor (Niraparib) and the cyclin-dependent kinase inhibitor dinaciclib downregulates MYC-driven homologous recombination and reduces cancer stem cell-like phenotypes." (PMID 33362856, 2020). "Here, our results initially interpret that, similar to other cancer types, the aggressive BC subtype TNBC acquires driver mutations, such as amplification-dependent overexpression of MYC and ASAP1, to progress, in spite of genetic heterogeneity." (PMID 32235890, 2020). "CDK7 is also a master regulator of important genes in cancer, as it regulates MYC expression in many cancer types." (PMID 32340192, 2020). "The protooncogene MYC is one of the transcription factors involved in the occurrence and development of many types of cancer and plays a key role in cell proliferation." (PMID 32855971, 2020). "MYC is one of the most well-known proto-oncogenes, contributing to tumorigenesis in many human cancers." (PMID 32411526, 2020). "Further, in 33 human cancers (n = 9502) MYC and TWIST1 predict poor survival (p=4.3×10−10), CCL2/IL13 expression (p<10−109) and TAM infiltration (p<10−96)." (PMID 31933479, 2020). "The interactome of c-MYC proto-oncogene provides a useful link to verify this suggestion because c-MYC in an important regulator of both ploidy and cancer." (PMID 33228223, 2020). "The relationship between MYC and proliferation in other cancer types also stipulates a role for MYC as a universal amplifier of transcription, alleviating constraints on cell growth and proliferation." (PMID 32681068, 2020). "Further investigation is needed to identify other pseudogene targets of MYC and determine their functions in cancer." (PMID 32127525, 2020). "Of these proteins, MYC has been shown to have the most substantial effects on reprogramming cancer metabolism in a type-specific manner." (PMID 32292719, 2020). "In particular, MYC, one of the most deregulated oncogenes in human cancer, has a DNA-G4 forming motif (MycG4) in its promoter." (PMID 32751510, 2020). "MYC, a dominant oncogene, in collaboration with SREBP, induces lipogenesis both in vitro and in vivo, and plays a role in the initiation and maintenance of tumorigenic growth in MYC-driven cancers." (PMID 33364199, 2020). "Various tyrosine kinases and oncoproteins such as MYC and RAS activate eIF4F during malignant proliferation, and oncogenic mutations upregulate various transcription factors thereby promoting further cancer progression." (PMID 32973493, 2020). "By inhibiting the expression of cell lineage specifiers while simultaneously inducing cell cycle progression, MYC proteins fulfill a major function in establishing self-renewal in ESCs, as well as in cancer stem cells." (PMID 33585251, 2020).
cancer (continued). "Targeted demethylation of transcripts coding for oncoproteins such as epidermal growth factor receptor (EGFR) and MYC can suppress proliferation of cancer cells." (PMID 32356894, 2020). "Although MYC inhibition would be a direct and powerful approach for the treatment of many types of cancers, MYC lacks a specific active site for binding by small molecules." (PMID 32748879, 2020). "CDK9 was involved in cancer progression through the BRD4-dependent recruitment of p-TEFb for the transcription of the MYC gene, which is a proto-oncogene controlling cell growth and cell cycle progression." (PMID 32848135, 2020). "Initiation of canonical Wnt signaling triggers transcription of several effector genes important for tumorigenesis and cancer progression, including c-MYC and cyclin D1." (PMID 33007980, 2020). "For example, MYC is a key oncogene in the MYC signaling pathway, and the dysregulation of MYC is related to the development of many cancers." (PMID 33343635, 2020). "Under normal circumstances, MYC expression is tightly regulated and has been shown to be deregulated in over 50% of human cancers." (PMID 32748879, 2020). "Mutations that increase the levels of two proteins known as MYC and TWIST1 in cells cause many human cancers." (PMID 31933479, 2020). "PP2A-activating drugs are known to be highly effective in reducing MYC activity in several types of cancers." (PMID 32110991, 2020). "SOX2 has a crucial role in the proliferation of cancer Cells through c-MYC in Wnt/β-catenin pathway." (PMID 33033513, 2020). "Dysregulation of MYC activity, which occurs most commonly via MYC gene amplification, is found in a variety of human cancer types: on average, 50% of human cancers have increased expression of MYC." (PMID 31638140, 2020). "In human cancers, MYC and the transcription activator MIZ1 (MYC-interacting zinc-finger protein 1 [ZBTB17]) can form a protein complex that represses the expression of MIZ1 target genes, most notably cyclin-dependent kinase inhibitor genes such as CDKN1A." (PMID 32407433, 2020). "Previously, c-MYC has been reported to regulate the expression of miR-7e-5p at the transcriptional level in cancer cell lines." (PMID 33168041, 2020). "Conversely, cancer cells need to modulate MYC expression and/or function according to the availability of nutrients, in order to avoid a metabolic collapse for better survival under poor nutrient conditions (e.g., glucose, glutamine, or EAA shortage)." (PMID 32651356, 2020). "Currently, the development of techniques targeting MYC for cancer therapy is being comprehensively investigated." (PMID 33014186, 2020). "Apart from that, the co-expression correlation of MYC with different subunits of SWI/SNF observed in various cancer types available with the TCGA’s (The Cancer Genome Atlas), PanCancer Atlas." (PMID 31932624, 2020). "Compounds that bind and stabilize the MycG4 structure have been shown to repress MYC expression and lead to cancer cell death." (PMID 32751510, 2020). "The aim of this review is to summarize the roles of MYC oncoproteins in the regulation of cancer cell metabolism, and to present the opportunities for targeting MYC-driven metabolic vulnerabilities in cancer treatment." (PMID 32651356, 2020). "This is because MYC is the most frequently amplified oncogene in human cancers and plays a critical role in transformation." (PMID 32481522, 2020). "The finding that c-MYC increases the expression of enzymes involved in proline synthesis from P5C has shed new light on the understanding of the proline cycle in cancer cells." (PMID 32824561, 2020). "For example, the well-known proto-oncogene MYC can be activated by pathological Wnt signaling in Wnt-driven cancers and also by diverse additional pathways in other cancers." (PMID 33092630, 2020).
cancer (continued). "(c) Comparison of relative percentage of monocyte and macrophage subpopulations, derived using CIBERSORT analysis of pan cancer TCGA cohort of 10366 patients from 33 cancers with tumors stratified as MYC/TWIST1High or MYC/TWIST1low (*p<0.05)." (PMID 31933479, 2020). "MYC proteins are often redundant in cancer and showing mutually exclusive expression patterns of MYC and MYCN in patient samples." (PMID 33585252, 2020). "We also discuss the therapeutic potential of targeting UPR signaling in cancers with MYC overexpression." (PMID 32310340, 2020). "It is well known that some classical cancer-related signalings such as MYC, Yap, Bmi1, Wnt/β-catenin, and PI3K/AKT/mTOR pathways were implicated in the hepatocyte-derived HCC formation." (PMID 32366840, 2020). "Increased MYC and TWIST1 expression was associated with significantly worse disease-free survival (DFS) (p=4.3×10−10) in the pan-cancer cohort." (PMID 31933479, 2020). "Targeting BRD4 with BET inhibitor results in transcriptional inhibition of MYC, which is the oncogenic driver and crucial cancer-dependent gene of MYCamp-G3-MB7,10." (PMID 33268769, 2020). "Using the same approach for the TCGA dataset, 16 cancers (~ 10%) were defined to be MYC hyperactivated by all three used MYC signatures." (PMID 33099868, 2020). "One of the first direct links between MYC and human cancers was the discovery of its role in Burkitt type B cell lymphoma." (PMID 33134177, 2020). "MYC, a well-studied proto-oncogene that is overexpressed in >20% of tumors across all cancers, is classically known as “undruggable” due to its crucial roles in cell processes and its lack of a drug binding pocket." (PMID 33322239, 2020). "It is well recognized that AKT, referred to as protein kinase B, and MYC, as a nuclear phosphoprotein, are the most prevalent driving oncogenes in cancer and the potentially regulatory function affecting glycolysis." (PMID 32635458, 2020). "MYC is known to target many protein-coding and lncRNA genes in different cancers, but a number studies have also pointed out that the reverse is also true and that lncRNAs regulate MYC activity at the post-translational level." (PMID 33134177, 2020). "Still, because NUAK1 protected cells from oncogenic MYC-induced metabolic stress and energy collapse, NUAK1 is also likely downstream of other oncogenes-induced metabolic stress, the hallmark of any cancer." (PMID 32754444, 2020). "MYC is highly expressed in many cancer types, but the abnormal activation of MYC is related to different enhancers." (PMID 33343635, 2020). "The small molecule BTYNB was reported to inhibit IGF2BP1 from binding to c-MYC mRNA and showed moderate cytotoxic effects in various cancer-derived cells." (PMID 32545414, 2020). "While MYC is known to be deregulated in a majority of cancers, its direct drug targeting has been elusive." (PMID 32923678, 2020). "Osteopontin (OPN) is a cytokine and integrin-binding ligand that is positively regulated by MYC and that is known to have pro-metastatic functions in cancer." (PMID 33081056, 2020). "Our previous study and other researchers’ studies demonstrated that THZ1 suppressed cancer proliferation by disturbing MYC function." (PMID 32690037, 2020). "MYC encodes a 439 residue nuclear bHLH-ZIP protein that, when expressed at supraphysiological levels, activates virtually all the hallmarks of cancer." (PMID 32715994, 2020). "For example, many cancers display MYC-dependent upregulation of the alternatively spliced PKM2 enzyme as a mechanism to enhance aerobic glycolysis." (PMID 33092283, 2020). "Treatment with PFI-1 induced inhibition of MYC expression through the downregulation of oncogene Aurora kinase B, leading to cancer cell apoptosis." (PMID 32218352, 2020).
cancer (continued). "One of the most frequently activated proto-oncogenes in human cancers is the c-MYC gene (MYC henceforth)." (PMID 33134177, 2020). "Targeting MYC overexpression is a challenge in cancer treatment as MYC plays a pivotal role in cellular functions, including cell cycle progression, metabolism, cell adhesion, signal transduction, transcription, and translation, protein biogenesis." (PMID 33176745, 2020). "The expression of MYC in cancer cells or as a transduced factor during reprogramming supports this switch by inducing hypoxia inducible factor 1a (Hif1A) and its downstream targets pyruvate dehydrogenase kinase and other glycolytic enzymes." (PMID 33585251, 2020). "A recent study described that U1 over-expression in PC-12 rat neuronal cell line upregulated cancer related genes, including MYC and FOS46." (PMID 31911652, 2020). "As already mentioned, MYC activation in cancer cells results in the increased expression of miR-105, which is then packed into exosomes and transported to surrounding CAFs." (PMID 33081056, 2020). "Under normal conditions, the expression of MYC is strictly controlled; however, in cancer, the activity of MYC is often deregulated, contributing to the initiation of tumorigenesis and maintenance of the disease." (PMID 33081056, 2020). "MYC is essential for oncogenesis and is activated through many different mechanisms in different cancers, such as chromosome translocations, gene amplification, or by SEs57." (PMID 33298918, 2020). "RiBi upregulation, modulated by oncogenes like MYC, is essential for the survival and proliferation of cancer cells." (PMID 31973211, 2020). "PVT1 is located at the 8q24 locus adjacent to MYC, which is highly expressed in many types of cancer and plays an important role in carcinogenesis." (PMID 32992461, 2020). "MYC is a proto-oncogene transcription factor, involved in pro-proliferative pathways, highly expressed in a wide range of cancers." (PMID 32879318, 2020). "Reports show that MYC-overexpressing cancer cells have increased sensitivity to apoptosis in response to cytotoxic drugs or radiation." (PMID 33322239, 2020). "In the context of cancer, MYC signaling affects cell adhesion and cell shape and reduces cell migration through modulation of the actin cytoskeleton." (PMID 32111741, 2020). "To assess the relationship between MYC activity and proliferation across cancer types, we evaluated MYC activity and cell proliferation rate in TCGA pan-cancer cohort using ssGSEA with MYC activity and proliferation signatures." (PMID 32681068, 2020). "Targeting MYC-onogene has significant therapeutic potentials for preferential splicing modulation in cancer." (PMID 32481522, 2020). "MYC is a master transcription factor that regulates a wide spectrum of target genes, and is found altered in several types of cancer." (PMID 32110991, 2020). "c-MYC as an oncogene in numerous cancer cells plays an important role in a myriad of biological processes, including cell growth, cell cycle progression and proliferation by cooperating with YAP and activating a large number of target genes." (PMID 32660514, 2020). "Since hypoxia and HIF-1 promote the glycolytic phenotype, the relationship between HIF-1 and c-MYC shows that c-MYC allows cancer cells to adapt to hypoxic microenvironment." (PMID 33028364, 2020). "In summary, the inhibition of CDK12 seems to be a promising tool for the treatment of various MYC-dependent cancers." (PMID 34316683, 2020). "Further investigation is necessary to define the effects of pharmacologic inhibition of PRMT5 and its safety margin in MYC-dependent cancers." (PMID 32481522, 2020). "Ectopic overexpression of the oncogenic MYC protein has been recently reported to alter circadian gene expression in cancer cell lines, although the molecular mechanism behind this MYC function is still highly debated." (PMID 32225100, 2020).
cancer (continued). "A prominent example of such a TF is MYC, a very well described oncogene and a crucial driver of cancer cell growth." (PMID 33208877, 2020). "The MYC protooncogene acts as a major inducer of protein synthesis in cancer cells by sustaining ribosome biogenesis through the stimulation of DNA PoI II and III activity and through increase in the levels of translation factors, and ribosomal DNA." (PMID 32151059, 2020). "Here, we highlight the application and efficacy of targeting UPR signaling in MYC‐hyperactivated cancers." (PMID 32310340, 2020). "Pathways related to the cell cycle (MYC targets, mitotic spindle, G2/M checkpoint and E2F targets) and DNA repair were also enriched in multiple cancer types, consistent with the established notion that mtDNA plays an important role in these pathways." (PMID 32024997, 2020). "One of the key anti-apoptotic genes involved in c-MYC driven cancer development is Myeloid cell leukemia 1 (MCL1)." (PMID 33187130, 2020). "In some cancers, the loss of CDKN1A expression upregulates genes that repress CDKN1A transcription, such as MYC." (PMID 32079343, 2020). "Peptidomimetics that disrupt MYC/MAX dimerization have shown efficacy in in vivo cancer model systems." (PMID 32225120, 2020). "Cancer cells become addicted to high levels of MYC to sustain their growth and therefore, are very sensitive to direct or indirect perturbation of MYC levels leading to proliferative arrest, differentiation or apoptosis." (PMID 31973211, 2020). "This review will focus on the direct and indirect impact of MYC in cancer aggressiveness and progression." (PMID 33081056, 2020). "The expression status of Forkhead box M1 and its relationship to etiology and outcomes of human cancers, as well as proteomic and genomic features related to MYC and the proximal MYC network have been reported for 33 cancer types in TCGA." (PMID 33072070, 2020). "On the other hand, c-MYC is a transcription factor and proto-oncogene which is highly regulated in cancers." (PMID 33551748, 2020). "JPH203 (also known as KYT-0353), a specific SLC7A5 inhibitor, can be evaluated as a MYC-selective cancer therapeutics in the future clinical trials." (PMID 32651356, 2020). "The deregulation of the MYC family of oncogenes, including c-MYC, MYCN and MYCL occurs in many types of cancers, and is frequently associated with a poor prognosis." (PMID 33628735, 2020). "MYC regulates multiple stages of cell metabolism and plays a key role in cancer cell metabolic reprogramming." (PMID 33251216, 2020). "Protein co-expression modules were linked to well-known PDAC hallmarks of cancer such as axon-guidance, EMT, oxidative phosphorylation, MYC targets and KRAS signalling, as well as potential new relationships to biological processes." (PMID 32860207, 2020). "MYC-associated protein X interactor-1 (MXI1) is an antagonist of the oncogenic MYC protein, and the deletion of the MXI1 gene causes many kinds of human cancers." (PMID 33489894, 2020). "Fibroblasts expressing MYC act locally at metastatic site and help to facilitate colonization by creating a lymphangiogenic microenvironment to support cancer cells’ survival." (PMID 33081056, 2020). "Our finding of c-MYC expression in mHNcSCC aligns with reports of c-MYC overexpression in other types of carcinoma." (PMID 32850316, 2020). "Consensus profiles indicated that the endothelial-like cells shared common carcinoma markers such as MYC, the epigenetic regulator JMJD3, the angiogenesis marker VEGFR2, and stem cell markers such as CD117." (PMID 32973147, 2020). "The activity of SIRT2 enhances N-MYC and c-MYC protein stability, promoting cancer cell proliferation." (PMID 30761005, 2019).